CCL19 (C-C motif chemokine ligand 19)
Diseases named in the same sentence as CCL19 in open-access papers (continued):
Sharing a sentence is not in itself a finding about the gene and the disease.
Arthritis (3 papers, 2023). Inflammation of a joint. "Chemotactic signals, such as recruitment of Ccr7+ T-cells via Ccl19 produced by macrophages, were also identified as a putative explanation for the dramatic increase in T-cells in Advanced arthritis (green arrow)." (PMID 37691918, 2023). "For instance, CCL3 KO mice showed milder clinical and histopathological scores in the CAIA model, whereas plt/plt mice, a naturally occurring CCL19 and CCL20 mutant strain, also showed mild arthritis in CIA model." (PMID 36860872, 2023).
B-cell Acute Lymphocytic Leukemia (3 papers, 2010 to 2022). "In childhood B-cell lymphoblastic leukemia cells, pre-B cells expressed CCR7 and migrated to CCL19, suggesting that CCR7 plays an important role in pre-B-cell lymphoblastic leukemia chemotaxis, whereas pro-B cells required the presence of the CD40 ligand to be CCL19/CCR7 responsive." (PMID 35203305, 2022).
central nervous system lymphoma (3 papers, 2010 to 2022). "A study showed that astrocyte-produced CCL19 was required for gliosis-induced central nervous system lymphoma progression." (PMID 35203305, 2022). "Similar to acute lymphoblastic leukemia, primary CNS lymphoma cells expressed CCR7, with CNS entry being dependent on CCR7 and its ligand, CCL19." (PMID 35203305, 2022).
endometriosis (3 papers, 2020 to 2024). The growth of functional endometrial tissue in anatomic sites outside the uterine body. "CCL19 is also present in the peritoneal fluid of endometriosis cases and regulates proliferation and invasion of endometriotic cells via the PI3K/AKT pathway." (PMID 38999962, 2024). "CCL19 is increased in blood from these volunteers, which has been found to be elevated in PF of infertile women with endometriosis." (PMID 38999962, 2024). "This is consistent with observations that the CCL19/CCR7 axis contributes to the pathogenesis of endometriosis by promoting proliferation and invasion of endometrial stromal cells." (PMID 39385609, 2024).
idiopathic pulmonary fibrosis (3 papers, 2022 to 2025). Idiopathic pulmonary fibrosis (IPF) is a nonneoplastic pulmonary disease that is characterized by the formation of scar tissue within the lungs in the absence of any known cause. "Interestingly, ‘CCL19+ adventitial fibroblasts’ and ‘CCN3+ adventitial fibroblasts’ overexpressed fibroblast activation protein (FAP), a marker of activated fibroblasts and cancer-associated fibroblasts, including in canine idiopathic pulmonary fibrosis and canine lung cancer." (PMID 40114924, 2025). "The CCR7/CCL19 axis seemed to play a role in airway smooth muscle hyperplasia in asthmatics and CCR7 was also expressed on fibroblasts in fibrotic areas of idiopathic pulmonary fibrosis patients." (PMID 35137398, 2022). "The lack of changes in Cxcl13, Ccl11, Ccl19, Xcl1, and Cxcl5 mRNA levels may be due to differences in bleomycin-induced pulmonary fibrosis and IPF, although models of bleomycin-induced pulmonary fibrosis are the most common experimental models for investigating IPF." (PMID 37122736, 2023).
liver fibrosis (3 papers, 2013 to 2023). "In the present study, of the seventy-four systemic inflammatory molecules analyzed, five were statistically significantly associated with the stage of liver fibrosis: MCP.4 (p = 0.032), CCL19 (p = 0.024), EN.RAGE (p = 0.014), SCF (p = 0.01), and IL18 (p = 0.054)." (PMID 37317244, 2023). "IPA of MYOC/CCL19 fibroblast gene expression correlating with the mRSS revealed several prominent pathways: senescence, hepatic fibrosis signaling, IL-6 signaling, STAT3 signaling, TGF-β signaling, protein ubiquitination, JAK/Stat signaling, and role of JAK1, JAK2 and TYK2 in interferon signaling." (PMID 35943798, 2022). "Another important event shown in the gene network model is the decrease of CCL19 in SPARC−/− mice, likely involved in the observed reduction in lymphocyte recruitment and process of liver inflammation which normally characterizes liver fibrosis as previously discussed." (PMID 23408952, 2013).
lymphopenia (3 papers, 2012 to 2024). Reduction in the number of lymphocytes. "During B cell responses to lymphopenia, the dominant cellular source of Notch ligands was restricted to a specialized subset of fibroblastic stromal cells lineage-traced with a Ccl19-Cre transgene and previously reported to have immune-interacting functions in secondary lymphoid organs." (PMID 35579963, 2022). "Dll1-expressing Ccl19-Cre+ stromal cells drive the B cell response to lymphopenia." (PMID 35579963, 2022). "In line with the data on the lymph node composition of CCL19- and CCL21-deficient plt mice, we hypothesized that this decrease in the cell surface expression of the receptor was a consequence, rather than the cause of the observed lymphopenia in the irradiated lymph nodes." (PMID 38951172, 2024).
osteoarthritis (3 papers, 2014 to 2024). A noninflammatory degenerative joint disease occurring chiefly in older persons, characterized by degeneration of the articular cartilage, hypertrophy of bone at the margins and changes in the synovial membrane. "The expression levels of CCL19, CCL21 and their receptor CCR7 in AS (n = 31) and osteoarthritis (OA, n = 21) LT were analyzed via real-time polymerase chain reaction (RT-PCR) and immunohistochemistry (IHC)." (PMID 25260647, 2014).
ovarian tumor (3 papers, 2014 to 2023). "CCL19 brought to the tumor site by endothelial progenitor cells (attracted to tumor sites because of ischemic signals) retrovirally infected with a CCL19 vector caused aggressive ovarian tumor growth to slow and reduced lung metastasis by 60% in a mouse model." (PMID 24762633, 2014). "CCL19 can substantially inhibit ovarian tumor growth and prolong survival after immunotherapy." (PMID 37841886, 2023).
scleroderma (3 papers, 2023 to 2025). Scleroderma is a rare autoimmune connective tissue disorder characterized by abnormal hardening of the skin and, sometimes, other organs. "Our fibroblasts in NEOLP and EOLP shared transcriptional similarity with fibroblasts from skins of scleroderma patients (including CCL19+APOE+CXCL12+ fibroblasts and SFRP2+PRSS23+ fibroblasts), which indicated an overlap between inflammatory features of fibroblasts across OLP and other diseases." (PMID 40574847, 2025). "In contrast, activated sublining FLS were transcriptionally similar to ACTA2+ myofibroblasts and WNT5B+ fibroblasts in the colon as well as two populations of dermal fibroblasts expanded in scleroderma as compared to healthy skin (CCL19+APOE+CXCL12+ and SFRP2hiPRSS23+THY1+)." (PMID 37277655, 2023). "In scleroderma, expression of CCL19 correlates with vascular inflammation of the skin." (PMID 37443817, 2023). "In our analysis of fibroblasts, FB1 was characterised as a pro-inflammatory or immune-interacting subtype by APOE, CYGB, C7, and IFGBP7 and this subset showed higher levels of CCL19 and PLA2G2A in scleroderma compared to the control." (PMID 37443817, 2023). "We demonstrated that both inflammation-driving subtypes, CCL19+ and SPARC+COL3A1+/FAP+THY+, are present in scleroderma, possibly promoting inflammation through chemotaxis and enhanced leucocyte infiltration." (PMID 37443817, 2023).
acute lymphoblastic leukemia (2 papers, 2022 to 2024). Leukemia with an acute onset, characterized by the presence of lymphoblasts in the bone marrow and the peripheral blood. "C-C Chemokine Receptor 7 (CCR7) mediates T-cell acute lymphoblastic leukemia (T-ALL) invasion of the central nervous system (CNS) mediated by chemotactic migration to C-C chemokine ligand 19 (CCL19)." (PMID 39273598, 2024).
adenoma (2 papers, 2011 to 2024). A neoplasm arising from the epithelium. "This notion is substantiated by CCL19 downregulation in adenomas with high-grade dysplasia and by an inverse association of CCL3 with polyp size and of CCL4 with number of polyps." (PMID 38338661, 2024). "Hyperplastic polyps differed from adenomas with significantly higher CCL19 (p = 0.017) and CCL4 (p = 0.007) expression in lesions." (PMID 38338661, 2024). "Both hyperplastic polyps and adenomas had significantly higher CCL19 expression than polyps with carcinomas: 1.84 (0.49–6.9) and 0.53 (0.38–0.74) vs. 0.03 (0–0.88), p = 0.002." (PMID 38338661, 2024). "CCL19, CCL21, CCL23, CCL5, were found to have reduced expression in the adenoma and adenocarcinoma compared to normal mucosa." (PMID 21249124, 2011). "In adenomas, only CCL4 was expressed at comparable level between the lesion and paired normal mucosa, while the expression of CCL3 (p = 0.006), CXCL2 (p = 0.023) and CCL19 (p = 0.016) was significantly higher in lesions." (PMID 38338661, 2024). "Likewise, CCL19 and CCL4 proteins were significantly more abundant in hyperplastic polyps than adenomas." (PMID 38338661, 2024).
allergic rhinitis (2 papers, 2012 to 2025). Inflammation of the nasal mucous membranes caused by an IgE-mediated response to external allergens. "Nasal administration of plasmids encoding CCL19/CCL21-Ser-DNA suppressed allergic responses in the murine allergic rhinitis model." (PMID 23118775, 2012). "We formerly showed the regulatory role of CCL19 and CCL21 in allergic rhinitis." (PMID 23118775, 2012).
B Cell Lymphoma (2 papers, 2016 to 2022). "In a recent study conducted with B cell lymphoma cells, inhibition of CCR7 endocytosis reverted repulsion to attraction in high CCL19 concentration gradients." (PMID 26824863, 2016).
carotid atherosclerosis (2 papers, 2022). A thickening and loss of elasticity of the walls of carotid arteries that occur with formation of atherosclerotic plaques. "Moreover, CCL19 is upregulated in carotid atherosclerosis, and it enables the enhancement of proliferative capacity and MMP-1 expression in vascular smooth muscle cells, thereby contributing to the pro-atherogenic potential." (PMID 35559253, 2022). "Elevated levels of circulating CCL19 and CCL21 can be found in patients with unstable angina pectoris compared to controls and enhanced levels of these chemokines were also observed in patients with carotid atherosclerosis, both systemically (CCL21) and within the lesion (CCL19 and CCL21)." (PMID 35600479, 2022).
dementia (2 papers, 2019 to 2023). Loss of intellectual abilities interfering with an individual's social and occupational functions. "We found several proteins associated with cognitive function and risks for incident dementia: IL10, LIF‐R, TWEAK, CCL19, IL‐17C, MCP‐4, TGF‐alpha, TNFB, CDCP1, etc." (PMID 37584418, 2023). "Our study highlights the changes and potential contributions of several chemokines (CXCL1, CCL3, CXCL5, CXCL6, CCL3, CCL19), interleukins (IL8, IL6-RA, IL18-BP), and other immune markers (OSM, ALCAM, OPG, CHIT1, YKL-40, STAMBP, MMP-9, MMP-10) in the prodromal and dementia phases of AD." (PMID 31694701, 2019).
dyslipidemia (2 papers, 2023 to 2025). "Moreover, the high expression of CCL19 was significantly associated with reduced activity of fatty acid degradation, which might lead to dyslipidemia and trigger the advance of NAFLD and AS." (PMID 37063958, 2023). "Conversely, the upregulation of proteins such as HGF and CCL19, along with increased inflammatory cytokines like IL-6, CXCL10, and CCL8, suggests an inflammatory environment that could predispose OBO individuals to the development of a metabolic syndrome." (PMID 40076884, 2025).
dysplasia (2 papers, 2024 to 2025). A usually neoplastic transformation of the cell, associated with altered architectural tissue patterns. "Eight of the 33 immune‐related markers (IL‐33, BCA‐1, GRO, CCL19 (MIP‐3B), sTNFRII, CXCL6 (GCP2), CRP and MIP‐1B) were inversely associated with dysplasia, with univariate ORs ranging from 0.30 (95%CI: 0.12–0.77) for IL‐33 to 0.76 (95%CI: 0.59–0.99) for MIP‐1B." (PMID 39482824, 2025). "While CCL19 was higher in low-grade than high-grade dysplasia in both normal and polyp tissue, CCL19 displayed an inverse pattern—it was higher in high-grade than low-grade dysplasia, also in both normal and polyp tissue." (PMID 38338661, 2024). "We found that patients with dysplasia had lower levels of IL‐33, BCA‐1, GRO, CCL19 (MIP‐3B), sTNFRII, CXCL6 (GCP2), CRP and MIP‐1B compared to gallstones patients without dysplasia." (PMID 39482824, 2025).
Fibroadenoma (2 papers, 2016 to 2020). A benign tumor of the breast characterized by the presence of stromal and epithelial elements. "Using machine learning to build predictive regression models, we selected a five-gene transcript set (ABCA8, APOD, CCL19, FN1, and PRAME) to discriminate between fibroadenomas and phyllodes tumors." (PMID 26961242, 2016).
follicular lymphoma (2 papers, 2021 to 2024). Follicular lymphoma is a form of non-Hodgkin lymphoma characterized by a proliferation of B cells whose nodular structure of follicular architecture is preserved. "Studies have revealed that low CCL19 expression is associated with unfavorable outcomes in cancers such as small cell lung cancer and follicular lymphoma." (PMID 39505867, 2024).
gastric tumours (2 papers, 2018 to 2021). "Homeostatic chemokines play a central role in the development of secondary lymphoid organs and TLSs,4, 12 and our earlier data revealed transcripts for Cxcl13, Ccl19, Ccl21 and Cxcl12 in laser microdissected TLSs from 6‐month‐old gp130F/F mice with well‐established gastric tumours." (PMID 29417587, 2018).
glioma (2 papers, 2023 to 2025). A benign or malignant brain and spinal cord tumor that arises from glial cells (astrocytes, oligodendrocytes, ependymal cells). "The IGLoS signature consists of six immune infiltration‐related genes associated with the survival of diffuse patients with glioma, which are CCL19, ICOSLG, IL11, PTGES, TNFAIP3, and TRAF3IP3." (PMID 40714831, 2025). "The differential methylation probe signal diminishes as the IGLoS Score increases, which is consistent with the high expression of the IGLoS signature (in the exception of CCL19) in gliomas, as the methylation of genes is often thought to silence gene expression." (PMID 40714831, 2025). "Next, we used the LASSO regression to further select six key regulators consisting of CCL19, ICOSLG, IL11, PTGES, TNFAIP3, and TRAF3IP3, and they were named the Immune Glioma Survival Signature (IGLoS signature)." (PMID 40714831, 2025). "In addition, strengthened T cell-glioma interactions through chemokine signaling, such as CCR5-CCL7/CCL8, CCR2-CCL7/CCL8/CCL11, CXCR3-CXCL9/CCL19, and CXCR6-CXCL16, were also revealed by a ligand-receptor analysis." (PMID 36959214, 2023). "Interestingly, as a known positive regulator, CCL19 demonstrated relatively more negative correlations in glioma, with the most significant negative correlations with VEGFA, CD276, and HMGB1." (PMID 40714831, 2025). "In the Gusu in‐house dataset consisting of 24 patients with glioma, TRAF3IP3, TNFAIP3, ICOSLG, IL11, and PTGES, showed a trend of increasing expression with increasing tumor grade, whereas CCL19 was not." (PMID 40714831, 2025).
injury (2 papers, 2023 to 2025). Damage inflicted on the body as the direct or indirect result of an external force, with or without disruption of structural continuity. "Ccl19 and Ccl21 genes are involved in modulating NF-κB pathway activation, and NF-κB signaling pathway is activated in LPS-induced lung injury animals." (PMID 37362920, 2023).
liver cancer (2 papers, 2021 to 2022). An epithelial or non-epithelial malignant neoplasm that arises from the liver. "Three cell line-derived xenograft (CDX) models of liver cancer were constructed, HepG2, Huh7, and LO2, to confirm whether AAV-CCL19 injected into tumors could effectively infect tumor cells and express CCL19." (PMID 34527749, 2021).
lung adenocarcinoma (2 papers, 2022). A carcinoma that arises from the lung and is characterized by the presence of malignant glandular epithelial cells. "Furthermore, elevated CCL19 levels were a good prognostic factor for lung adenocarcinoma patients." (PMID 35203305, 2022). "Additionally, elevated CCL19 was a good prognostic factor in lung adenocarcinoma patients, suggesting that CCR7/CrkL interactions are variable and might be tumor type specific." (PMID 35203305, 2022). "CCL19, along with CCR7, acted as clinically prognostic factors in lung adenocarcinoma." (PMID 35550569, 2022).
migraine (2 papers, 2024 to 2025). "Nine proteins—including CD6 and beta-NGF—were positively associated with migraine, while others like CCL19 showed inverse correlations." (PMID 40426647, 2025).
neuroblastoma (2 papers, 2020 to 2022). Neuroblastoma (NB) is the most common solid, extracranial childhood tumor. "Walker and colleagues found that changes in the CCL19 signal transduction pathway can lead to defects in the migration of dendritic cells in neuroblastoma, which in turn affects tumor progression." (PMID 32963529, 2020). "Interestingly, CCL22 was found in supernatants of cocultured DC and neuroblastoma cells, but activation of DC was needed to induce CCL19 and T-cell migration in the same settings." (PMID 36923280, 2022). "Interestingly, besides MYCN amplification that is a bad prognosis factor in neuroblastoma, a recent study found that transcription of five genes including CCL19 and CD1C, could predict better prognosis." (PMID 36923280, 2022). "Altogether, our results suggest that CCL2 produced by neuroblastoma cells initiate the recruitment of monocytes, myeloid and plasmacytoid DCs, and that among these cells, the CD1c+ subset when activated may recruit T cells by means of CCL19/CCL22 secretion." (PMID 36923280, 2022). "In vitro, supernatants from DCs cocultured with neuroblastoma cell lines and activated contain CCL22 and CCL19, and are chemotactic for both CD4+ and CD8+ T cells." (PMID 36923280, 2022). "Altogether, these data suggest that CCL19 and CCL22 produced by activated DC play an important role in recruiting T cells to the neuroblastoma microenvironment in vitro and in vivo." (PMID 36923280, 2022). "To decipher which APC may be responsible for CCL19 and CCL22 secretions in neuroblastoma tumors, we analyzed correlations between these chemokine levels and APC-specific markers." (PMID 36923280, 2022). "We observed CCL19 production after R848 activation of DC in the presence or not of neuroblastoma cell lines." (PMID 36923280, 2022). "In MYCN-nonamplified neuroblastoma, CCL2 produced by neuroblastoma cells induces the recruitment of antigen-presenting cells (DCs and monocytes/macrophages), allowing infiltration by T cells, in link with CCL19 and CCL22 production, hence favoring immune responses." (PMID 36923280, 2022). "Overall, our findings highlighted a major role for CCL2/CCR2 axis in monocytes, myeloid and plasmacytoid cells recruitment toward MYCN-nonamplified neuroblastoma, and suggest that the recruited myeloid DCs will further recruit T lymphocytes by means of CCL19 and CCL22." (PMID 36923280, 2022). "To confirm the involvement of CCL19 and CCL22 in T-cell migration, we analyzed CCL19 and CCL22 secretion by DCs (comprising PDC, cDC1, and cDC2), purified from healthy donors blood, that were cocultured for 24 hours in the presence or not of neuroblastoma cell lines and activated or not." (PMID 36923280, 2022).
periodontitis (2 papers, 2024 to 2025). An acute or chronic inflammatory process that affects the tissues that surround and support the teeth. "In advanced human periodontitis, T and B/plasma cells predominate, for which CXCL13 and CCL19 expression from the ICAM1+ fibroblasts may be important as they are chemotactic for B and T cells, respectively." (PMID 39650645, 2024).